EGFR (epidermal growth factor receptor)
Diseases named in the same sentence as EGFR in open-access papers (continued):
Sharing a sentence is not in itself a finding about the gene and the disease.
oral cavity cancer (7 papers, 2003 to 2024). A primary or metastatic malignant neoplasm involving the oral cavity. "Our study is one of the first studies analyzing the effectiveness of EGFR antibodies for oral cavity cancers." (PMID 33953747, 2021). "By clarifying the clonality of the EGFR gene status in paired tumor specimens, we can determine whether EGFR amplified cells bear the invasive characters in metastasis or recurrence in oral cavity cancer." (PMID 28854970, 2017). "The importance of epidermal growth factor receptor (EGFR) status in oral cavity carcinoma remains unclear." (PMID 27841120, 2016). "One possible explanation may be cetuximab’s targeting of EGFR as a part of PCE and the characteristic nature of oral cavity cancer relating to EGFR." (PMID 39011480, 2024).
oral mucositis (7 papers, 2018 to 2026). Inflammation of the mucous membranes of any of the structures in the mouth. "Diarrhoea and oral mucositis caused by EGFR‐TKIs tend to occur later than nausea and emesis caused by platinum‐based drugs, and this may explain why the appetite‐related QOL was only affected at 6 weeks after initiating first‐line systemic therapy." (PMID 39351653, 2024). "The strength of this study is that the incidence of oral mucositis induced by anti-EGFR antibody combined with 5-FU based chemotherapy was reported in the real world setting." (PMID 30290786, 2018). "It was also reported that the incidence of oral mucositis was 5 to 7% when an anti-EGFR antibody was used as monotherapy." (PMID 30290786, 2018). "Oral mucositis is the main issue faced by anti-EGFR treatment." (PMID 38576484, 2024). "Therefore, we conducted a retrospective cohort study to examine the incidence and severity of oral mucositis in patients who were receiving anti-EGFR antibodies concomitantly with 5-FU." (PMID 30290786, 2018). "As a crucial regulator of EGFR sorting and degradation, USP8 inhibition potently suppresses EGFR signaling (a promising strategy for EGFR-driven cancers) but may simultaneously induce epidermal and gastrointestinal toxicities, such as rash, itching, dry skin, oral mucositis, diarrhea, and anorexia." (PMID 41565619, 2026). "Although the mechanism of oral mucositis induced by the anti-EGFR antibody concomitant with 5-FU was not clarified, anti-EGFR therapy may deteriorate 5-FU-induced oral mucositis by interfering with the wound healing process due to blockage of EGF." (PMID 30290786, 2018).
ovarian adenocarcinoma (7 papers, 2008 to 2025). An adenocarcinoma that arises from the ovary. "The EGFR-MEK-ERK signaling pathway has been reported to mediate ovarian adenocarcinoma cell motility and invasiveness." (PMID 33817145, 2019). "We studied in vitro uptake and functionality of EGFR-targeted liposomes in human ovarian adenocarcinoma (SKOV-3 and SKOV3.ip1) cells." (PMID 22844475, 2012). "Receptor mediated cellular uptake and cytotoxic efficacy of EGFR-targeted liposomes were investigated in human ovarian adenocarcinoma (SKOV-3 and SKOV3.ip1) cells." (PMID 22844475, 2012). "This study investigated the antiproliferative, pro-apoptotic, and immunomodulatory effects of Hes and ADR in human ovarian adenocarcinoma cells (SKOV3), focusing on Forkhead box P3 (FOXP3) and epidermal growth factor receptor (EGFR) signaling pathways." (PMID 41301890, 2025).
rectal adenocarcinoma (7 papers, 2005 to 2025). "Previously, EGFR overexpression has been found to be associated with shorter survival in patients with rectal adenocarcinoma." (PMID 38650801, 2024). "In conclusion, EGFR positivity in pre-op biopsy samples seems to be associated with shorter survival, and increased EGFR expression in post-treatment resection specimens predicts aggressive behavior in patients with rectal adenocarcinoma who received NRT/NCRT." (PMID 38650801, 2024). "In our study, we used immunohistochemistry, which is an easily applicable method in many laboratories, to assess EGFR expression in rectal adenocarcinoma cases who have received NRT/NCRT." (PMID 38650801, 2024). "In this study, we evaluated EGFR expression in pre-treatment biopsy and post-treatment surgical specimens using immunohistochemistry in patients with rectal adenocarcinoma who received neoadjuvant radio- and/or chemotherapy (NRT/NRCT)." (PMID 38650801, 2024). "One activating BRAFL597Ralteration (exon 15) was identified (10.0%) in a 56-year-old male with bulky rectal adenocarcinoma with synchronous metastases that progressed through 9 months of first-line anti-EGFR therapy." (PMID 28178681, 2017). "We wished to ascertain whether a correlation exists between the expression of EGFR and treatment outcome in a group of patients with rectal adenocarcinoma who had undergone preoperative radiotherapy (RT)." (PMID 15967033, 2005).
skin squamous cell carcinoma (7 papers, 2013 to 2023). A carcinoma arising from the squamous cells of the epidermis. "The epidermal growth factor receptor (EGFR) is overexpressed in virtually all squamous cell skin cancers." (PMID 37417890, 2023). "Further study shows that overexpression of DSG2 in human skin squamous cell carcinoma cell line enhances EGFR activation and increases cell proliferation and migration through a c-Src and EGFR dependent manner." (PMID 32095325, 2020). "A previous study showed that both EGFR small interfering RNA (siRNA) and EGFR inhibitors increase the expression of several differentiation markers, including keratin 1, keratin 10, and involucrin in primary human keratinocytes, intact epidermis, and skin squamous cell carcinomas." (PMID 33096942, 2020).
tongue tumor (7 papers, 2015 to 2022). "To verify the enhanced EGFR signaling by I227T/N236D mutation in vivo, we performed the immunohistochemical staining of phosphorylated EGFR in xenograft tongue tumor tissues." (PMID 33246423, 2020). "Mean H-score of phosphorylated EGFR was significantly higher in I227T/N236D TβRII tongue tumor sections than in wild-type sections (p < 0.05)." (PMID 33246423, 2020). "This was investigated in a mouse orthotopic tongue tumor model with EGFR-specific nanobodies conjugated randomly to the photosensitizer IRDye700DX." (PMID 31544818, 2019). "IRDye800CW-labeled anti-EGFR nanobodies could clearly delineate orthotopic tongue tumors in mice, and even enabled the identification of a lymph node metastasis." (PMID 31544818, 2019). "A similar localization pattern for EGF-Rh:EGFR-GFP complexes was observed in tongue tumors, although a lower number of EGF-Rh-labeled cells was detected, probably, due to a strong autofluorescence of muscle cells in the red channel interfering with the detection of weak endosomal EGF-Rh signals." (PMID 29268862, 2017). "Furthermore, we demonstrated its utility in detecting and guiding resection of cervical SLNs using ICG, as well as primary tongue tumors and hypopharyngeal tumors using an EGFR-targeting nanobody conjugated to IRDye 800CW." (PMID 25344146, 2015). "In this study one cetuximab-sensitive cell line (UT-SCC-14, established from a tongue tumour) with a high EGFR expression and one resistant cell line (UT-SCC-2, established from a floor of mouth tumour) with a low EGFR expression were used." (PMID 28756482, 2017). "When combined EGFR and CD4 expression was analyzed, it was found that EGFR+/CD4+ expression was associated with never smokers (p=0.03), tongue tumor disease site (p=0.03), T1 tumors (p=0.02), N0 tumors (p=0.002), no LVI (p=0.02) and no BI (p=0.01)." (PMID 35957892, 2022). "Orthotopic EGFR-overexpressing (data not shown) OSC-19-luc2-cGFP tongue tumors were clearly identifiable using both Artemis and Pearl after injection of 7D12-800CW." (PMID 25344146, 2015).
transitional cell carcinoma (7 papers, 1991 to 2024). A malignant neoplasm arising from the transitional epithelium, usually affecting the urinary bladder, ureter, or renal pelvis. "Notably, SDCBP interacts with EGFR in urothelial cell carcinoma and modulates EGFR signaling." (PMID 38649770, 2024). "We describe the use of a recombinant canine anti-EGFR monoclonal antibody (mAb), can225IgG, conjugated to the photo-absorber, IR700DX, in three EGFR expressing canine transitional cell carcinoma (TCC) cell lines as a prelude to possible canine clinical studies." (PMID 29721181, 2018).
Airway obstruction (6 papers, 2022 to 2025). Obstruction of conducting airways of the lung. "Notably, observational studies suggest that COPD is independently associated with reduced rates of EGFR mutations and ALK rearrangements, with mutation frequency inversely correlated to airway obstruction severity." (PMID 40507634, 2025). "In addition to degrading elastase and dissolving other proteins, NE stimulates mucin production and secretion by the EGFR cascade, which can aggravate the inflammatory response and contribute to airway obstruction in COPD patients." (PMID 36523421, 2022). "Additionally, our findings suggest that altered intracellular calcium levels may directly affect EGFR signaling and bronchial contractility, leading to airway cytoskeletal remodeling and adipose tissue accumulation, which can exacerbate airway obstruction." (PMID 41148307, 2025). "Finally, EGFR inhibition may alleviate mucus hypersecretion by suppressing mechanical-stress-induced ERK/MUC5AC signaling, offering a targeted strategy to reduce airway obstruction." (PMID 40995116, 2025).
Anorexia (6 papers, 2011 to 2026). Lack of desire to eat (loss of appetite). "There was a significant relationship between polymorphisms in germline EGFR and severe AEs or anorexia." (PMID 36637703, 2023). "EGFR rs2293348 C > T (C/T genotype) was also significantly associated with grade ≥ 1 or ≥ 2 anorexia (Online Resource, Table F1, p < 0.001 or p = 0.023, respectively, in an additive model)." (PMID 36637703, 2023). "The most common adverse events were rash (40.0% in the EGFR-TKI plus thymosin group and 38.5% in the EGFR-TKI group), diarrhea (23.1% vs 25.4%), dry skin (20.0% vs 20.8%) and anorexia (9.2% vs 10.0%)." (PMID 34123814, 2021). "The most common adverse events were rash (40.0% in the EGFR-TKI plus thymosin group and 38.5% in the EGFR-TKI group), diarrhea (23.1% and 25.4%, respectively), dry skin (20.0% and 20.8%, respectively) and anorexia (9.2% and 10.0%, respectively)." (PMID 34123814, 2021). "Although the mechanism responsible for EGFR-TKI-induced anorexia has not been elucidated, one hypothesis for anorexia induction is gastric mucosal injury, since inhibition of EGFR in gastric parietal cells can interfere with gastric mucosal membrane protection and repair of mucosal injury." (PMID 36637703, 2023).
atopic dermatitis (6 papers, 2018 to 2025). "The epidermal growth factor (EGFR) on keratinocytes protects this barrier, and its dysfunction leads to atopic dermatitis-like skin disease." (PMID 34833113, 2021). "In addition, the correlation between ErbB1 downstream signaling and increase in the abundance of Corynebacterium has been demonstrated mechanistically in a model of atopic dermatitis, whereby EGFR inhibition results in dysbiosis (the appearance of Corynebacterium species) and inflammation." (PMID 29924794, 2018).
brain injuries (6 papers, 2012 to 2025). "It has been hypothesized that EGFR activation is a master signal transduction pathway of the cellular activation process in response to different brain injuries and causes the characteristics of the reactive astrocyte/microglia phenotype." (PMID 22747893, 2012). "In brain injuries, the shedding of EGFR ligands such as TGFα activate EGFR and prevent the generation of neurons facilitating gliogenesis and contributing to the generation of gliogenic niches in areas of brain damage." (PMID 30949480, 2019). "Studies have indicated that blockade of the EGFR pathway may attenuate reactive astrogliosis by inhibiting cell cycle progression and protect against ischaemic brain injury in rats." (PMID 35815278, 2022). "Regulating EGFR activity might be relevant when developing strategies to promote endogenous neurogenesis in brain injuries." (PMID 30949480, 2019). "Our results suggest that TGF-α or EGFR may be used as targets to regenerate brain injuries." (PMID 38037126, 2023). "Regulating EGFR activity might be relevant when developing strategies to promote endogenous neurogenesis in brain injuries and understanding the mechanisms that activate this receptor may lead to the identification of molecular targets to regenerate brain injuries." (PMID 30949480, 2019). "In brain injuries, the metalloproteinase ADAM17 releases the transforming growth factor alpha (TFGα) which activates the epidermal growth factor receptor (EGFR), thus promoting the creation of a gliogenic/non-neurogenic environment." (PMID 37047560, 2023). "The ability of p66KO NSCs to resist apoptosis and differentiate without EGFR-ERK signalling highlights the potential of targeting p66Shc in conditions where growth factor signalling is disrupted, such as neurodegenerative diseases or brain injuries." (PMID 40593476, 2025).
carcinosarcoma (6 papers, 2014 to 2024). A malignant tumor composed of a mixture of carcinomatous and sarcomatous elements. "We describe the clinical course of a 63-year-old female with epidermal growth factor receptor (EGFR)-mutant NSCLC who initially responded to osimertinib but eventually developed carcinosarcoma." (PMID 38813335, 2024). "Out of the five cases (70-75%), three cases were carcinosarcomas, and two cases were SCCs that displayed IHC expression to EGFR." (PMID 36247506, 2022). "Five of our cases (71%), the three carcinosarcomas and the two SCCs showed immunohistochemical positivity to EGFR." (PMID 25030022, 2014). "Previously, we evaluated the expression of tyrosine kinase receptors such as EGFR and HER-2 in benign mixed tumors, carcinomas in mixed tumors, and carcinosarcomas." (PMID 27490467, 2016). "Targeting of EGFR, HER2, PDGFR and immunosuppressive molecules have been suggested as potential strategies from molecular studies of gynaecological carcinosarcomas; however, data are limited and the vast majority of data are derived from UCS, rather than OCS." (PMID 35715633, 2022).
clear cell carcinoma (6 papers, 2014 to 2023). "Collectively, these results confirm that GALNT6 promotes the aggressive behavior of ovarian endometrioid and clear cell carcinoma cells by regulating EGFR glycosylation and activity." (PMID 28388560, 2017). "Clear cell carcinoma (CCC) of the ovary renders chemoresistant through epidermal growth factor receptor (EGFR) and the downstream targets of MEK/ERK pathway." (PMID 26263999, 2015). "Moreover, the erlotinib treatment reduced tumor weight in PDXs of clear cell carcinoma with overexpression of epidermal growth factor receptor (EGFR)." (PMID 37296950, 2023).
colorectal adenoma (6 papers, 2016 to 2021). An adenoma that arises from the colon or rectum. "More interestingly, combination treatment of APCmin/+ mice using AMI-1 and cetuximab, a therapeutic EGFR monoclonal antibody, showed significant synergy to reduce the formation of colorectal adenomas in mice." (PMID 33853662, 2021). "Primary objective of our study is to evaluate the level of EGFR expression on colorectal adenomas surface compared to normal cells and CRC." (PMID 28157706, 2017). "The primary endpoint of our study was to demonstrate the EFGR expression on colorectal adenomas, and that is the reason why we used the clone 113 anti-EGFR that had yet been reported as very sensitive for EGFR expression in CRC." (PMID 28157706, 2017). "In addition, activation of mutations in the KRAS (or RAS) oncogene occur at a similar frequency in both SBA and colorectal adenoma tumors, which suggests a potential role for EGFR inhibition in a subset of patients with SBA." (PMID 28536826, 2017). "However, data remain scares about the level of EGFR expression on colorectal adenomas, in contrast with CRC." (PMID 28157706, 2017). "This whole of data leads to validate EGFR as a potential biomarker of colorectal adenomas." (PMID 28157706, 2017). "This expression was also significantly superior to adjacent normal colon crypts (p < 0.001), and was confirmed during an ex vivo colonoscopy prodecure performed in 14 mices, by the use of a cetuximab (anti-EGFR)-tracer that could clearly delineate all colorectal adenomas." (PMID 28157706, 2017). "However there are other primary antibodies that showed similar outcomes to assess the EGFR expression both in CRC and colorectal adenomas." (PMID 28157706, 2017).
Epstein-Barr virus infection (6 papers, 2016 to 2021). An infection that is caused by Epstein-Barr virus. "What's more, 5 of the first 20 enriched KEGG pathways are related to PI3K-Akt signaling pathway, Epstein-Barr virus infection, Kaposi sarcoma-associated herpesvirus infection, proteoglycans in cancer, and EGFR tyrosine kinase inhibitor resistance." (PMID 34992668, 2021).
Fibroadenoma (6 papers, 2017 to 2025). A benign tumor of the breast characterized by the presence of stromal and epithelial elements. "They found that PTs with fibroadenoma-like areas were more likely to harbor mutations in exon 2 of MED12, a gene often altered in benign breast fibroepithelial tumors, whereas PTs without fibroadenoma-like areas more commonly had mutations in EGFR and other known cancer genes." (PMID 29043292, 2017).
liposarcoma (6 papers, 2018 to 2025). A usually painless malignant tumor that arises from adipose tissue. "In addition, as a control, we assessed the expression of epidermal growth factor receptor (EGFR), which is often upregulated in liposarcoma, and for which we have already described a RevTM19." (PMID 39924591, 2025). "EGFR (R108K) and NF2 (K20*) were the two possible driver mutations that were detected in 2 separate samples and have not been described before in WD/DD liposarcoma." (PMID 29731991, 2018). "Moreover, several low-molecular-weight multi-kinase inhibitors targeting MET, AXL, IGF1R, EGFR, VEGFR2 and PDGFR-β could be effective in the types of liposarcoma characterized by abnormalities in PI3K/Akt/mTOR signaling and the associated deregulation of other cascades." (PMID 38254762, 2024).
liver dysfunction (6 papers, 2015 to 2025). "Re-administration of EGFR-TKIs often exacerbates liver dysfunction and, in such cases, patients should be switched to other EGFR-TKIs." (PMID 33466795, 2021). "Therefore, it could be hypothesized that the overexposure to the drug may lead to a potentially higher efficacy of EGFR TKIs among patients with liver dysfunction resulting from liver metastases." (PMID 26248464, 2015). "Patients receiving combined targeted therapy (anti-angiogenic drugs, EGFR inhibitors) had a higher incidence of liver dysfunction, although the difference was not statistically significant (P = 0.056)." (PMID 40881884, 2025).